TIMP1 (TIMP metallopeptidase inhibitor 1)
Diseases named in the same sentence as TIMP1 in open-access papers (continued):
Sharing a sentence is not in itself a finding about the gene and the disease.
thyroid cancer (23 papers, 1999 to 2026). "The level of TIMP1 mRNA expression was found to be an independent diagnostic marker of malignant thyroid neoplasms." (PMID 23548070, 2013). "We found that DPP4, TIMP1 and TYRO3 were associated with a better prognosis and survival in patients with thyroid cancer, while FABP4, NR4A1 and SNCA were associated with a poor prognosis and survival in patients with thyroid cancer." (PMID 36407322, 2022). "In terms of immune cells, Wu believes that TIMP1 is a key gene involved in the infiltration of immune cells in thyroid cancer lymphatic metastasis." (PMID 36419192, 2022). "Previous studies have shown that EGF stimulates TIMP-1 expression in extravillous trophoblasts and thyroid carcinoma cells." (PMID 27509063, 2016). "TIMP1 has been shown to be overexpressed in both liver and peritoneal metastases from patients with colorectal adenocarcinoma and malignant thyroid neoplasms." (PMID 23548070, 2013). "In the present study we examined the expression of one member of TIMPs, TIMP-1, in 39 thyroid tumour specimens and two thyroid carcinoma cell lines (NPA and SW579)." (PMID 10098765, 1999). "Our data clearly questioned the relevance of TIMP1 as a marker of thyroid cancer." (PMID 19893615, 2009). "Our analysis concludes that TIMP1, LOX, CD276, IFNA1, TLR2, and POSTN are identified as thyroid cancer biomarkers, which lead to the different clinical courses of a woman older than 55 years old with papillary thyroid cancer." (PMID 36120433, 2022). "Here, we performed LASSO analysis and identified 6 critical fibroblasts related factors (PCOLCE2, APOD, APOE, TIMP1, HTRA3 and MT1A) and calculated the fibrosis scores based on their expression in patients with thyroid cancer." (PMID 36387901, 2022). "Compared to TIMP1 and LOX, the relation between TLR2 and thyroid carcinoma was unclear, especially in PTC." (PMID 36120433, 2022). "Four candidate proteins, galectin-3, NAG-1, TIMP-1, and osteoprotegerin (OPG), were identified as potential biomarkers of thyroid cancer." (PMID 34208730, 2021). "An association between elevated TIMP1 concentrations and BRAF mutations has been found in thyroid cancer, but not in CRC29,30." (PMID 39789100, 2025). "TIMP1, a secreted protein best known for its inhibitory effects on matrix metalloproteinase 9 (MMP9), has been documented as overexpressed in multiple malignancies including lung, prostate, and thyroid cancers —a finding consistent with our observations in LUAD." (PMID 41187171, 2025). "Univariate Cox regression analysis was further applied to assess the prognostic value of DEFRGs, and we found that 4 DEFRGs (APOE, P = 0.004; TSC22D1, P = 0.025; TIMP1, P = 0.029; HTRA3, P = 0.007) may act as independent factors for overall survival of thyroid cancer." (PMID 36387901, 2022). "Above all, in our results, TIMP1, LOX, and POSTEN had different expressions no matter what type of thyroid cancer and papillary thyroid cancer; even in pure classic PTC, high expression of those genes also predicted a poor prognosis." (PMID 36120433, 2022). "However, it is not clear whether TIMP-1 serves only as a biomarker of cancer progression or functions to promote cancer progression; thus, it could serve as an important cancer therapeutic target in thyroid cancer." (PMID 34208730, 2021).
lung adenocarcinoma (22 papers, 2015 to 2025). A carcinoma that arises from the lung and is characterized by the presence of malignant glandular epithelial cells. "It has been shown that in lung adenocarcinoma, p38α caused increased cell proliferation by promoting the expression of TIMP-1." (PMID 41002380, 2025). "Aberrant TIMP1 overexpression in cancer-associated fibroblasts stimulates tumor progression through CD63 in lung adenocarcinoma." (PMID 39769169, 2024). "TIMP-1 has been associated with different solid tumor progression but its clinical significance in lung adenocarcinoma remains inadequately explored." (PMID 29507665, 2018). "MiR-210 is related to TIMP-1 expression in lung adenocarcinoma cells, promoting tube formation activity in human umbilical vein endothelial cells (HUVECs) and accelerating lung adenocarcinoma metastasis." (PMID 41049292, 2025). "In lung adenocarcinoma cells, Tissue Inhibitor of Metalloproteinases-1 (TIMP-1) induces miR-210 upregulation through a CD63 Antigen (CD63)/PI3K/AKT/HIF-1-dependent pathway." (PMID 38612567, 2024). "Next, a survival analysis of the validated ligands revealed that the high expression ligand signals VEGFA, TIMP1, and SPP1 were significantly associated with a lower chance of survival in patients with lung adenocarcinoma." (PMID 37189418, 2023). "In the validation set, VEGFA, TIMP1 and SPP1 were still found to be significantly associated with the survival of lung adenocarcinoma patients." (PMID 37189418, 2023). "Another study reported that upon overexpression of the tissue inhibitor of metalloproteinases-1 (TIMP-1) in lung adenocarcinoma cells, miR-210 accumulates in TEXs (in vitro and in vivo), promoting tube formation activity in recipient HUVECs." (PMID 32825667, 2020). "This relationship of IL-6 with TIMP-1 expression was evident in primary tumor tissues of lung adenocarcinoma." (PMID 31443242, 2019). "We have also reported on the antiapoptotic activity of TIMP-1 in a lung adenocarcinoma, with delineation of the signaling pathway downstream of TIMP-1 leading to its antiapoptotic function." (PMID 29507665, 2018). "TIMP-1 levels correlated with shorter overall survival in patients with lung adenocarcinoma [log rank P = 8.1e-14, with a hazard ratio (HR) of 3.17 (2.3–4.37)]." (PMID 29507665, 2018). "Formalin-fixed paraffin embedded lung adenocarcinoma tissue and adjacent normal tissue samples were subjected to in situ expression detection of miR-125a-5p and TIMP-1 by ISH (in situ hybridization)." (PMID 29507665, 2018). "Our earlier studies have identified increased angiogenic activity and aggressive tumor kinetics in TIMP-1 overexpressing H2009 lung adenocarcinoma cells." (PMID 29507665, 2018). "Previously, we have shown that overexpressing TIMP-1 in H2009, a lung adenocarcinoma cell line resulted in aggressive tumors when implanted in the mouse brain." (PMID 29507665, 2018). "We have sought to define the relationship between TIMP-1 and miRNA by knocking down TIMP-1 in high TIMP-1 expressing lung adenocarcinoma cell lines." (PMID 29507665, 2018). "Our earlier studies using H2009 lung adenocarcinoma cells, implanted in the CNS, showed that TIMP-1 overexpressing H2009 cells (HB-1), resulted in more aggressive tumor kinetics and increased vasculature." (PMID 26366732, 2015). "Overexpressing TIMP-1 in a lung adenocarcinoma cell line H2009 resulted in an approximately 3-fold increased expression of Bcl-2, with a marked reduction in apoptosis upon staurosporine treatment." (PMID 26366732, 2015). "In the present study, we have investigated the role of TIMP-1 overexpression in H2009, lung adenocarcinoma cell line." (PMID 26366732, 2015). "Previously, we have shown that overexpressing TIMP-1 by stably transfecting pBK-CMV-TIMP-1 plasmid in lung adenocarcinoma cell line NCI-H2009 injected into the mouse brain, resulted in aggressive tumors with increased microvessel density." (PMID 26366732, 2015).
lung adenocarcinoma (continued). "Similarly, in lung adenocarcinoma, NET-associated multi-omics signatures—also involving TIMP1—were linked to metabolic remodeling and immunosuppression." (PMID 41170378, 2025). "We also analyzed the expression of TIMP-1 in different tumor stages of lung adenocarcinoma (LUAD)." (PMID 31443242, 2019). "In a recent research, tissue inhibitor of metalloproteinases-1 (TIMP-1) was reported to lead to a pro-tumourigenic increase of miR-210 in lung adenocarcinoma cells along with their exosomes and E2F3, a downstream target of miR-210, was decreased in the presence of TIMP-1." (PMID 28947999, 2017). "This study was undertaken to define the role of TIMP-1 in lung adenocarcinoma cell line." (PMID 26366732, 2015). "Overall, VEGFA-, TIMP1, and SPP1-mediated regulatory networks may not only be the main cause of macrophage changes, but also these three signals may be markers of malignant changes in lung adenocarcinoma." (PMID 37189418, 2023). "Profiling TIMP-1 in an array of lung adenocarcinoma cell lines, we found that the cell lines depicted as KRAS-independent appeared to express higher levels of TIMP-1 compared to cell lines that were KRAS-dependent." (PMID 41002380, 2025). "Important regulatory molecules (VEGFA, TIMP1, SPP1, etc.)of macrophages in lung adenocarcinoma were identified by the gene regulatory network method." (PMID 37189418, 2023). "MRNA expression levels of TIMP1, S100P, HMMR, F2RL1, KRT6A, and SLC2A1 were significantly increased in lung adenocarcinoma cell lines compared to16HBE, which were consistent with our bioinformatics analysis results." (PMID 35830566, 2022). "Hsa-mir-145 formed the third regulatory module for lung adenocarcinoma c with lncRNA C1orf220, which ranked second in potential lncRNAs, and mRNAs (COL1A2, COL3A1, SPP1, TIMP1 and CDH1)." (PMID 36138770, 2022). "This study explored that TIMP-1 mRNA expression was increased in A549 and H1299, and high expression of TIMP-1 was closely related to the metastasis of lung adenocarcinoma." (PMID 35830566, 2022). "The results showed that ACAN, CDKN3, GRIN2A, IL17A, KCNQ2, TIMP1, and UCHL1 were significantly up-regulated in lung adenocarcinoma cells." (PMID 36147496, 2022). "This indicates that the co-expression of TIMP-1 and IL-6 has a negative impact on the survival of lung adenocarcinoma patients." (PMID 31443242, 2019). "Targeting VEGFA, TIMP1, and SPP1 may be a potential therapeutic strategy for lung adenocarcinoma." (PMID 37189418, 2023).
ischemic stroke (21 papers, 2010 to 2025). A stroke disorder caused by obstruction of blood flow to the brain, due to thrombotic (local blood clot formation) or embolic (due to a blood clot or other material traveling from another site) event. "Higher serum TIMP‐1 levels were associated with increased risk of cognitive impairment at 3 months after acute ischaemic stroke, independently of established risk factors." (PMID 32431079, 2020). "Studies evaluating the associations between TIMP‐1 levels and risk of cognitive impairment after ischaemic stroke are sparse." (PMID 32431079, 2020). "Higher circulating levels of tissue inhibitor of matrix metalloproteinases (TIMP)-1 early after ischemic stroke have been associated with lower survival." (PMID 31319804, 2019). "Similar findings were observed in a clinical study with the relative increase in MMP-9/TIMP-1 ratio independently associated with symptomatic ICH in ischemic stroke patients." (PMID 26973468, 2016). "Moreover, the MMP-9/Timp-1 ratio is independently associated with cerebral edema and symptomatic intracerebral hemorrhage in ischemic stroke patients, indicating a critical role for the MMP9/Timp1 ratio in the regulation of BBB integrity." (PMID 37649100, 2023). "In addition, higher circulating TIMP-1 levels at day 1 of ischemic stroke have been previously associated with poor neurological outcome and lower survival." (PMID 31319804, 2019). "In addition, higher circulating TIMP-1 levels at day 1 of ischemic stroke have been associated with poor neurological outcome and lower survival." (PMID 31319804, 2019). "Interestingly, there has been reported that circulating TIMP-1 levels are associated with brain edema in ischemic stroke patients." (PMID 24728097, 2014). "Furthermore, TIMP‐1 was reported to be associated with white matter hyperintensities and low brain volume, which could increase risk of the development of ischaemic stroke and mild cognitive impairment." (PMID 32431079, 2020). "High levels of TIMP-1 have been found in infracted brain tissue and in the blood of ischemic stroke patients." (PMID 35629249, 2022). "Previous studies indicated that circulating levels of TIMP‐1 significantly increased after acute cerebral ischaemia and played a role in the prognostication of ischaemic stroke." (PMID 32431079, 2020). "Compared with ischaemic stroke patients with both lower serum TIMP‐1 and MMP‐9 levels, the ORs were 2.83 (95% CI, 1.74‐4.60) for cognitive impairment defined by MMSE and 2.99 (95% CI, 1.81‐4.95) by MoCA in participants with both higher levels." (PMID 32431079, 2020). "Among the upregulated genes, Hspa1b, Ccl2, Cxcl2, Ccl3, Serpina3n, Timp1, H19, Hspb1, Ccl20, and Cxcl1 were found to demonstrate significant upregulation in pathological phase of ischemic stroke." (PMID 25861363, 2015). "Previously there were found higher circulating levels of MMP-9 and MMP-10 and TIMP-1 in ischemic stroke patients than in controls." (PMID 26162891, 2015). "In monocytes of 25 ischemic stroke patients, TIMP-1 expression was increased during the first days after the event." (PMID 23158556, 2012). "TIMP-1 is essential to protected against blood-brain barrier disruption after ischemic stroke by regulating activities of MMPs." (PMID 21731773, 2011). "Based on network pharmacological analysis, the core targets of AS-TMP combination for anti-ischemic stroke are TIMP-1, VEGFA, MMP9, etc., which are mainly related to apoptosis, cell proliferation, and vascular smooth muscle cell proliferation, focusing on the VEGF signaling pathway." (PMID 40869300, 2025). "In order to further investigate whether TIMP-1 played an essential role in the mechanism of combined AS and TMP treatment for ischemic stroke, siRNA technology was used to interfere with the TIMP-1 gene in OGD cell models." (PMID 40869300, 2025).
ischemic stroke (continued). "Third, besides IGF-1, DPSC-CM contains the TIMP-1 and TIMP-2 which were associated with inhibition of matrix metalloproteinase (MMP) protein levels, thereby restoring BBB integrity and improving cerebral edema following ischemic stroke." (PMID 36181630, 2023). "Accordingly, we studied the relationship between serum TIMP‐1 and cognitive impairment in patients with acute ischaemic stroke and investigated whether TIMP‐1 provided any predictive value for cognitive impairment." (PMID 32431079, 2020). "Previous studies found higher brain concentrations of TIMP-1 in infarcted than in healthy brain areas, higher monocytes expression of TIMP-1 in ischemic stroke patients than in healthy subjects, and higher circulating levels of TIMP-1 in ischemic stroke patients than in controls." (PMID 31319804, 2019). "Indeed, the correlation of MMP-9/TIMP-1 ratio with cerebral edema was even stronger than that of MMP-9 alone following ischemic stroke in rats." (PMID 26973468, 2016). "TIMP-1 concentrations are elevated early after ischemic stroke onset." (PMID 23158556, 2012). "However, the impact of serum TIMP‐1 on subsequent cognitive impairment among patients with ischaemic stroke remains unknown." (PMID 32431079, 2020). "Both TIMP‐1 and MMP‐9 were suggested to have important role in the prognostication of ischaemic stroke, and the coexistence of higher serum TIMP‐1 and MMP‐9 was associated with highest risk of adverse clinical outcomes after ischaemic stroke." (PMID 32431079, 2020). "TIMP-1 and MMP-9 are key factors closely related to BBB injury in ischemic stroke." (PMID 40869300, 2025). "The results of the mechanism study showed that the combination of AS-TMP could adjust the expression levels of TIMP-1 and MMP-9 in the animal serum and cortical brain tissue of rat models of ischemic stroke." (PMID 40869300, 2025). "However, TIMP1 and PTX3 were also downregulated in astrocytes from Il1−/− mice but were both shown to play a protective role after ischemic stroke." (PMID 35384588, 2022). "Third, we did not collect dynamic changes of TIMP‐1 levels before and after ischaemic stroke in the population." (PMID 32431079, 2020). "However the prognostic value of circulating levels of tissue inhibitor of matrix metalloproteinases (TIMP)-1 and MMP-10 in functional outcome of ischemic stroke patients has been scarcely studied." (PMID 26162891, 2015). "In addition, there have been found higher production of TIMP-1 in infarcted brain tissue compared to healthy brain areas, and higher expression of TIMP-1 in monocytes of ischemic stroke patients than in healthy controls." (PMID 26162891, 2015). "There have been found higher TIMP-1 concentrations in infarcted brain tissue compared to healthy cerebral areas, higher expression of TIMP-1 in monocytes of ischemic stroke patients than in healthy controls, and higher circulating TIMP-1 levels in ischemic stroke patients than in healthy controls." (PMID 26162891, 2015). "However the prognostic value of circulating levels of TIMP-1 and MMP-10 in functional outcome of ischemic stroke patients has been scarcely studied." (PMID 26162891, 2015). "In vivo experiments and the levels of MMP-9 and TIMP-1 in serum and the infarcted cortex were determined through multiple strategies, including ELISA, immunohistochemistry, RT-PCR, and Western blotting, which were the key factors closely related to BBB injury in ischemic stroke." (PMID 40869300, 2025). "Increased serum TIMP‐1 may be an adaptive physiological response to enhanced MMP‐9 activity, in order to regulate excessive proteolytic activity and maintain extracellular matrix homeostasis in the acute phase ischaemic stroke." (PMID 32431079, 2020). "TIMP1 unfolds protective neurovascular effects in ischemic stroke, whereas both MMP12 and osteopontin receptor CD44 may critically contribute to ischemic brain damage, suggesting that these proteins/genes may all be important therapeutic targets in ischemic stroke." (PMID 35752654, 2022).